CD70 (CD70 molecule)
Diseases named in the same sentence as CD70 in open-access papers (continued):
Sharing a sentence is not in itself a finding about the gene and the disease.
tumor (continued). "These promising results demonstrated that CD70-targeted CAR-T cells can not only enhance tumor elimination but also overcome some of the immunosuppressive challenges typically encountered in solid tumors like HNSCC." (PMID 40312353, 2025). "Cancer-related genes, such as CD70, VEGFA, and ENTPD1 (also known as CD39), which are reportedly associated with immune suppression, tumor proliferation, immune escape, and drug resistance, exhibited increased expression in patients in the neural-high group." (PMID 41147013, 2025). "In a ccRCC patient-derived xenograft model, (18F)RCCB6 exhibited substantial tumor-specific uptake (10.63% ± 1.21% ID/g), with CD70 blockade significantly reducing this signal (0.53% ± 0.04% ID/g; p = 0.002), confirming target engagement." (PMID 40896423, 2025). "These ADC toxicities predominantly involve hematologic complications, suggesting payload-related mechanisms despite CD70’s tumor-selective expression." (PMID 40896423, 2025). "CD70 CAR-T-cell therapy delayed tumor growth and extended survival, probably due to the high expression of CD70 in U251 cells." (PMID 40474210, 2025). "CAR T-cells engineered to target CD70 can directly eliminate tumor cells while potentially reversing immune suppression." (PMID 40940995, 2025). "Persistent CD70 expression promotes tumor growth, inhibits apoptosis, and facilitates immune evasion." (PMID 40650111, 2025). "CD70 is aberrantly overexpressed in diverse tumours with limited normal tissue expression, making it a compelling diagnostic and therapeutic target." (PMID 40629902, 2025). "When observing tumor samples of CD70-high patients, CD3 staining showed that only a fraction of T-cells express the molecule (arrows), with most CD3 + cells being CD70-negative (asterisks)." (PMID 40205178, 2025). "Clinical outcomes vary markedly across different tumour types, with CD70‐targeted strategies generally achieving more favourable responses in hematologic malignancies compared with solid tumours." (PMID 40629902, 2025). "CD70 RNA signals were predominantly located in tumor nests (B dashed line areas), but also scattered in stroma." (PMID 40205178, 2025). "Studies conducted in pancreatic ductal adenocarcinoma (PDAC), AML and GBM revealed that CD70 is differentially upregulated in CSC subpopulations as compared to differentiated tumor cells." (PMID 41233805, 2025). "This aberrant CD70/CD27 interaction contributes to immune evasion by influencing the tumor microenvironment (TME) and promoting tumor progression." (PMID 40484866, 2025). "CD70 knockdown in fibroblasts abrogated these effects and reduced tumor proliferation and cytokine expression in vivo." (PMID 41510255, 2025). "Collectively, these data show that ADP-520 TRuC T cells exhibit reduced signs of autoactivation and terminal differentiation while retaining strong efficacy against CD70-expressing target cells of multiple tumor indications." (PMID 40519930, 2025). "In this last study, we found a strong interaction between tumor cells expressing CD70 and T lymphocytes expressing CD27." (PMID 40148586, 2025). "In animal models, the combination of a CD70 antibody with anti–PD-1 therapy exhibits a pronounced synergistic anti-tumor effect, markedly enhancing immunotherapeutic responses." (PMID 41278473, 2025). "Multivariate analysis confirmed that CD70 expression and tumor stage were significant prognostic factors for OS, while CD27 was not." (PMID 40205178, 2025). "CD70 interacts with CD27 on T-cells to promote tumor proliferation, survival, and immune suppression via the NF-κB and PI3K pathways." (PMID 40940995, 2025). "Emerging evidence also indicates that CD70 can transmit tumor-intrinsic signals, engaging pathways such as PI3K/AKT and MAPK to promote proliferation, invasion, and epithelial–mesenchymal transition." (PMID 41510255, 2025).
tumor (continued). "CD70, minimally expressed in normal tissues but upregulated in malignancies, regulates immune cell function physiologically yet promotes tumor progression." (PMID 40896423, 2025). "In contrast, knockdown of CD70 in NHDF1-TGFβ fibroblasts significantly suppressed tumor size (representative images), weight, and volume compared with the shCon group." (PMID 41510255, 2025). "Preclinical studies have shown that CAR T-cells targeting CAIX, c-MET, and CD70 exhibit significant anti-tumor activity in xenograft models." (PMID 40940995, 2025). "The heterogeneity of CD70 expression across tumour cells also evidently undermines the efficacy of CD70‐specific CAR‐T cell therapy." (PMID 40629902, 2025). "Our findings show that tonic signaling induces terminal differentiation, excessive activation, exhaustion and reduced tumor-killing ability in anti-CD70 CAR-T cells during in vitro culture." (PMID 40165944, 2025). "Together, the role of sodium citrate in reducing exhaustion and enhancing anti-tumor activity is verified in both anti-CD70 and anti-MSLN CAR-T cells." (PMID 40165944, 2025). "In this retrospective study, we analyzed 190 surgically resected SCLC tumor samples using immunohistochemistry (IHC) for CD70 and CD27 expression and RNAscope for CD70 RNA detection." (PMID 40205178, 2025). "CD70 was expressed in 46% of tumors, primarily within tumor nests, with lower expression in stromal areas." (PMID 40205178, 2025). "Due to the presence of the antibody, these drugs can locate CD70‐positive tumour cells, forming an ADC–antigen complex." (PMID 40629902, 2025). "By comparing different CAR design strategies, it was demonstrated that trCD27‐41BB‐zeta CAR‐T cells exhibited the strongest IFN‐γ production and were capable of eradicating CD70‐positive tumours in mice." (PMID 40629902, 2025). "Collectively, our findings identify CD70 as a stress-inducible signaling hub that links DNA damage, inflammation, and tumor–stromal communication in skin carcinogenesis." (PMID 41510255, 2025). "MEPCE is a methyltransferase that adds a monomethyl cap to small nuclear RNA, and CD70 is expressed readily on tumor cells and enhances cancer and regulatory T cell survival." (PMID 40078282, 2025). "We intracranially implanted 80% CD70+ and 50% CD70+ U251 cells to construct a high tumor burden model." (PMID 40474210, 2025). "In a recent study, a comparable CRISPRa technique was utilized to simultaneously activate multiple endogenous genes such as Cd70, Cd80, Cd86, Ifnα4, Ifnβ1, and Ifnγ, triggering anti-tumor adaptive immune clearance of tumor cells in a mouse model." (PMID 41283440, 2025). "Protein-level validation by immunohistochemistry further revealed increased CD70 expression in the relapsed tumor (MC3Ri) relative to the primary tumor." (PMID 40876452, 2025). "Recent studies have highlighted a link between CD70 and the generation and maintenance of CSCs, demonstrating its critical role in tumor progression, drug resistance and immune evasion." (PMID 41233805, 2025). "The combined action of IL-15 and CAR-NK effectively eliminated CD70-positive tumor cells and increased the survival rate of mice harboring CD70-positive tumors." (PMID 40705122, 2025). "Our previous results demonstrate that CD70 is not only expressed in epidermis but also detected in dermis Among stromal elements, CAFs drive drive tumor progression primarily through secretion of pro-inflammatory cytokines and growth factors." (PMID 41510255, 2025). "Exosomal biomarkers such as miR-2276-5p (OC), miR-141-3p (RCC), and tumor-specific surface markers (e.g., CD147, CA9, CD70) are emerging as key diagnostic tools." (PMID 40303340, 2025). "In vivo, co-injection of CD70-expressing fibroblasts with cSCC cells accelerates tumor growth, whereas CD70 knockdown impairs tumor progression and reduces PCNA, IL6, and MCP3 expression, confirming its functional relevance in the tumor microenvironment." (PMID 41510255, 2025).
tumor (continued). "Aberrant CD70 expression has been reported in hematologic and solid malignancies, where it can contribute to immune evasion and tumor progression." (PMID 41510255, 2025). "Preclinical studies have demonstrated that CD70-targeted agents, such as antibody–drug conjugates (ADCs) and CAR-T-cells, exhibit anti-tumor activity in CD70-positive tumors." (PMID 41154432, 2025). "In tumor cells, CD70 engages with CD27, resulting in secretion of soluble CD27 (sCD27) and proteolytic shedding of the CD27 ectodomain." (PMID 40597436, 2025). "Anti-CD70 monoclonal antibodies suppress tumor progression by augmenting immune-mediated cytotoxicity." (PMID 40896423, 2025). "Although intratumoral injection of OAd-GFP or CD70 CAR-T cells suppressed tumor progression and prolonged mouse survival, the CAR-TOAd−GFP combination had a strong antitumor effect, leading to tumor regression and long-term survival." (PMID 40474210, 2025). "Beyond its direct effects on epithelial proliferation, CD70 shapes the tumor immune microenvironment by modulating the cytokine and chemokine milieu." (PMID 41510255, 2025). "They notably expanded upon activation of their CD70-directed alloreactivity, supporting their enhanced in vivo persistence and tumor-killing capacity." (PMID 40885188, 2025). "We further validated these findings using a panel of primary RCC patient-derived tumor lines, each with varying levels of CD70 expression." (PMID 40885188, 2025). "In SCLC tumors, CD70 exhibited a diffuse signal with lower expression in vimentin-positive tumor cell clusters but was present in vimentin-positive CAFs in the stroma." (PMID 40205178, 2025). "These targets were selected to represent diverse tumor scenarios, with varying expression of surface CAR target antigens (i.e., CD70) and NKR ligands (e.g., MICA/B, ULBPs, CD112, and CD155), thus modeling RCC-associated tumor heterogeneity." (PMID 40885188, 2025). "CD70 offers a promising target due to its tumor-restricted expression and minimal off-target effects." (PMID 40896423, 2025). "In a murine MM model, CD70 CAR-NK cells achieved superior tumor control and significantly prolonged survival, underscoring their therapeutic potential in relapsed or refractory MM." (PMID 41303706, 2025). "This upregulation of CD70 promoted Tregs accumulation and T cell exhaustion, contributing to an immunosuppressive tumour microenvironment." (PMID 40629902, 2025). "Colocalization studies showed that CD70 protein exhibits a fluke, diffuse signal with a conspicuous complementarity with vimentin staining in tumor nests of CD70-high patients." (PMID 40205178, 2025). "Our findings reveal that fibroblast-derived CD70 amplifies cytokine production via NF-κB, thereby enhancing keratinocyte proliferation and 3D tumor spheroid formation." (PMID 41510255, 2025). "Flow cytometry validated the high, albeit heterogeneous, expression of CD70 on RCC tumor cells across different patients, supporting its utility as a promising CAR target." (PMID 40885188, 2025). "CD70 expression was predominantly found within tumor nests and to a lesser extent in the stroma, while CD27 was primarily located in the stromal compartment." (PMID 40205178, 2025). "This new CAR design combines targeting of CD70 on tumors, enhancement of T cell tumor trafficking via expression of the IL-8 receptor, and inhibition of LAIR1 by secreting soluble LAIR2 to remodel the immunosuppressive TME." (PMID 40591413, 2025). "The in vitro functionality of CD70-CAR NK cells was investigated against a panel of tumor and CAF cell lines with varying CD70 expression." (PMID 38331849, 2024). "Patients had a median of three lines of prior treatment, and median CD70 expression on tumours was 100%." (PMID 38539542, 2024). "In CRC, our group also detected CD70+ CAFs especially at the invasive front and more abundantly in invasive tumor specimens." (PMID 38331849, 2024).
tumor (continued). "Particularly in CRC, our study has demonstrated that these CD70+ CAFs promote tumor migration and regulate immune escape via accumulation of regulatory T cells." (PMID 38331849, 2024). "Tumor growth curve showed VHH CD70 CAR-T cells efficiently controlled RCC growth, leading to complete remission in mice by day 28 (11C9 and 8B4 CAR-T), day 31 (2A5 CAR-T) and 5/7 mice by day 66 (9D8 CAR-T)." (PMID 38637886, 2024). "Here, we demonstrated in vitro and in vivo the therapeutic potential of IL-15 armored CD70-CAR NK cells to eliminate both CD70+ tumor cells and, most interestingly, also tumor-promoting CD70+ CAFs in CRC and PDAC." (PMID 38331849, 2024). "CD70 expression, elevated in recurrent GB, plays a crucial role in tumor aggressiveness and maintenance." (PMID 39328617, 2024). "In mouse xenograft model, CD70 CAR-T cells efficiently controlled RCC tumor growth, leading to complete remission." (PMID 38637886, 2024). "CD27, when it binds to its native ligand CD70, can promote T cell proliferation and differentiation into effector and memory T cells, which have potent anti-tumor potential." (PMID 38601154, 2024). "CD70, typically expressed by tumour cells, serves as a receptor‐ligand binding to the CD27 receptor on T cells' surface." (PMID 39031800, 2024). "Considering that CD70 is restricted to a subpopulation of CAFs that harbors clear tumor-promoting capacities, selectively targeting CD70+ CAFs has the ability to positively modulate the TME in CRC and PDAC patients." (PMID 38331849, 2024). "Consistent with tumor kinetics, CD70-CAR-IL-15 NK cells significantly improved survival of Raji-bearing mice." (PMID 38331849, 2024). "Considering the specific expression on tumor cells and CAFs, CD70 emerges as an ideal target for CAR-based immunotherapy." (PMID 38331849, 2024). "To test if these co-stimulatory molecules played a role in local and abscopal tumor control in hRT/lena-treated mice, we blocked CD70, CD83, and CD86 during hRT/lena treatment by co-administration of blocking antibodies." (PMID 38646638, 2024). "In our in vitro experiments, anti-CD70 CAR-T cells effectively eliminated CD70-positive tumor cells while sparing CD70-negative cells." (PMID 38637886, 2024). "Using PDOs co-cultured with CAFs they showed that CD70-CAR-NK cells in combination with IL-15 is needed for an effective eradication of low- and high-expressing CD70 + tumor cells and CAFs." (PMID 39261955, 2024). "In this study, CD70 was selected as a therapeutic target for CAR-T therapy due to its high expression in various tumor tissues." (PMID 39906740, 2024). "Experimental validation confirmed that manipulating the CD70 levels impacted ccRCC tumor cell viability, particularly in the presence of a T cell co-culture." (PMID 39796121, 2024). "The antitumor activity of CD70 CAR-T cells was consistent with the ability of expansion after tumor cell challenge." (PMID 38637886, 2024). "All CD70 CAR-T eliminated tumor cells and proliferated during the first round coculture, but lost their capacity of killing and/or proliferation during repetitive co-cultures." (PMID 38637886, 2024). "The Marcela Maus laboratory evaluated the anti‐tumor activity of CD70 CAR‐T cells through the NSG Molm13 AML model and found that in co‐culture with AML, CD70‐CAR‐T cell activity was impaired by the soluble CD27 form was attenuated." (PMID 38712978, 2024). "It has also been reported that CD70, via a receptor-dependent pathway, induces T-cell apoptosis and promotes tumor migration." (PMID 38342925, 2024). "CD70-CAR T cells in AML patients who are positive for CD70 have demonstrated considerable targeting or tumor toxicity towards normal hematopoietic stem cells and myeloid progenitor cells." (PMID 39697338, 2024). "CD27, a prominent protein in the tumor microenvironment, modulates cellular activity by engaging with CD70." (PMID 38504180, 2024).
tumor (continued). "Mature DCs express co-stimulatory molecules including CD80, CD86, CD40 and CD70, that enables DCs have the capacity to activate T cells and NK cells in tumor immune-surveillance, and directly kill tumor cells." (PMID 38554155, 2024). "Yet, these data reveal the therapeutical potential of CD70 as a target on both tumor cells and the TME in CRC and PDAC patients." (PMID 38331849, 2024). "Functional evaluation of CD70-directed CAR NK cells indicated that IL-15 stimulation is essential to obtain effective elimination of CD70+ tumor cells and CAFs, and to improve tumor burden and survival of mice bearing CD70+ tumors." (PMID 38331849, 2024). "Aberrant CD70 expression has been reported to accelerate immune evasion and increase malignant phenotypes in many tumor types, including pleural mesothelioma." (PMID 38473788, 2024). "Of note, a higher CD70 expression by CAFs compared to tumor cells was showed in CRC cases (14,9% vs. 2,2%)." (PMID 39261955, 2024). "It was demonstrated that CXCR1 and CXCR2-modified CD70 CARs downregulated the expression of exhaustion markers on T cells and upregulated the migration of T cells in the tumor." (PMID 38201305, 2024). "We identified tumor cell lines with high CD70 expression, such as U251, ACHN and 786-0, as positive models, while CASKI and BXPC3 served as negative controls for further evaluation." (PMID 39906740, 2024). "In this regard, the immune checkpoint molecule CD70 is an interesting candidate with expression in a wide array of solid tumors, nearly absent on healthy tissue, and an apparent involvement in anti-tumor immune suppression." (PMID 38331849, 2024). "In line with our previous in vitro data on tumor cells, CD70-CAR NK cells showed improved reduction of CAF growth over time compared to MOCK NK cells in all three CAF cell lines." (PMID 38331849, 2024). "These CD70-positive CAFs facilitate tumor migration and increase Treg frequency, contributing to immune escape in CRC and underscoring the potential of CD70-targeting antibodies in therapy." (PMID 38693104, 2024). "In this study, using RNA-seq data from the TCGA database and in-house immunohistochemical staining of tumor resections, we identified CD70-expressing tumor cells and CAFs as a promising therapeutic target in PDAC and CRC patients." (PMID 38331849, 2024). "CD70 emerges as interesting target, due to its stringent expression pattern in healthy tissue and its apparent role in tumor progression in a considerable amount of malignancies." (PMID 38331849, 2024). "Even more, we are the first to show a CD70-directed therapy that can target both the tumor cells and the TME in solid tumors." (PMID 38331849, 2024). "The binding ability of the site-specifically labeled VHH was determined in tumor models expressing CD70." (PMID 37093350, 2023). "We also unveiled that CD70-targeted cusatuzumab treatment destabilized Tregs in a manner dependent on the CD70 expression level on tumor cells, the CD27 expression level on CD4+ T cells, and the CD4+/CD8+ ratio in the TME." (PMID 37024479, 2023). "In cancer biology, CD70 can facilitate immune evasion and tumor progression in the tumor immune microenvironment." (PMID 37732314, 2023). "PET imaging showed specific radiotracer accumulation in CD70 expressing human tumor xenografts, which was efficiently blocked by prior injection of unlabeled anti-CD70 VHH (p = 0.0029)." (PMID 37093350, 2023). "Here the authors show that tumor-restricted CD70 correlates with regulatory T cell abundance and suppressive activity in NPC and that CD70 blockade improves response to anti-PD1 in preclinical models." (PMID 37024479, 2023). "Next, we investigated the tumor targeting of the radiotracer [68Ga]Ga-NOTA-anti-CD70 VHH in nude mice bearing CD70high tumors (786-O), or CD70low tumors as negative control using μPET/CT imaging." (PMID 37093350, 2023).